CCR2 (C-C motif chemokine receptor 2)
Diseases named in the same sentence as CCR2 in open-access papers (continued):
Sharing a sentence is not in itself a finding about the gene and the disease.
rheumatoid arthritis (46 papers, 2005 to 2026). A chronic, systemic autoimmune disorder characterized by inflammation in the synovial membranes and articular surfaces. "Of note, cluster 3 failed to express the subset of Tph-associated chemokines (e.g., Cxcl13, Ccr2, Cx3cr1) described in rheumatoid arthritis and other conditions, a finding consistent with previous reports that chemokine expression by Tph cells is context dependent." (PMID 39087473, 2024). "Although, CCR2 has been implicated in range of inflammatory disease including rheumatoid arthritis, tumors, we are reporting for the first time that high expression of CCR2 may be due to high OCPs exposure in EOC sample." (PMID 29576811, 2018). "CCR2 orchestrates preferential homing of GMSC‐derived extracellularvesicles to inflamed joints in rheumatoid arthritis." (PMID 41503025, 2026). "In contrast, in two well-established murine rheumatoid arthritis (RA) models, Ccr2 null mice showed enhanced bone erosion and osteoclast activity leading to more severe disease than wild-type mice, accompanied by marked infiltration of inflammatory cells." (PMID 37371471, 2023). "Anti-CCR2 monoclonal antibody therapy (MLN1202) has been investigated safely in people with rheumatoid arthritis, where it reduced monocyte counts and free CCR2 on circulating monocytes." (PMID 35686910, 2022). "A phase IIa clinical trial of a human CCR2 antagonist (MLN1202) in patients with active rheumatoid arthritis found that treatment with the CCR2 antagonist reduced free CCR2 levels on CD14+ monocytes by at least 57% and up to 94%." (PMID 36566220, 2022). "Earlier, we reported the up-regulation of CCR1 and CCR2 in PB B cells activated in vitro and in circulating B and T lymphocytes in patients with rheumatoid arthritis." (PMID 32708233, 2020). "CCR2 is a key regulator of monocyte and macrophage migration, with potential roles in diverse inflammatory disease including rheumatoid arthritis and inflammatory bowel disease." (PMID 29487134, 2018). "CCR2 is considered a proinflammatory mediator in many inflammatory diseases such as rheumatoid arthritis." (PMID 21991368, 2011). "CCR2 is normally involved in the infiltration of monocytes in inflammatory diseases such as rheumatoid arthritis and its ligands include CCL2, CCL7, and CCL8." (PMID 20976171, 2010). "Monoclonal anti-CCR2 antibody therapy, which is already used for rheumatoid arthritis may be a treatment option against MODS during severe acute pancreatitis and other inflammatory diseases." (PMID 36300116, 2022). "CCL2 and CCR2 are extensively studied in rheumatoid arthritis." (PMID 30937315, 2019). "Particular attention is given to the PD-1hi CXCR5− Bcl6low T peripheral helper (Tph) cell population in rheumatoid arthritis, which infiltrates inflamed synovium through expression of chemokine receptors such as CCR2 and augments synovial B cell responses via CXCL13 and IL-21." (PMID 30190721, 2018). "This redundancy has been appreciated for some time and may explain the lack of clinical efficacy of selective biologic and small molecule CCR2 antagonists in diseases such as rheumatoid arthritis." (PMID 19906300, 2009). "MCP-1 is a cytokine in the CC chemokine family that coordinates the migration of multiple cell types through C-C motif chemokine receptor 2 (CCR2) under physiological and pathological conditions, such as rheumatoid arthritis (RA) and other autoimmune diseases." (PMID 36554439, 2022). "However, an imbalance in favor of highly inflammatory CCR2+ macrophages can lead to pathological alterations contributing to postinfarction heart failure or resulting in inflammatory conditions such as atherosclerosis and rheumatoid arthritis (RA)." (PMID 33669804, 2021). "Antibodies against CCR1, CCR2, and CCR5 have been developed for the treatment of rheumatoid arthritis." (PMID 37760825, 2023). "CCR2 and CCL2 have been extensively studied in inflammatory diseases, particularly in rheumatoid arthritis." (PMID 36109442, 2023).
rheumatoid arthritis (continued). "Nevertheless, using the same mouse monoclonal anti-CD192-Alexa Fluor 647 antibodies, we demonstrated the cell-surface expression of CCR2 on monocytes and B lymphocytes in PB of patients with rheumatoid arthritis and patients with chronic lymphocytic leukemia." (PMID 35408790, 2022). "Moreover, studies in patients with rheumatoid arthritis (RA) showed that fibroblast-like synoviocytes (FLS) constitutively express CCR2, CCR5, CXCR3,and CXCR4; in addition, stimulation with CCL2, CXCL12, CXCL9, and CXCL10 enhances FLS migration and proliferation." (PMID 28883822, 2017). "The aim of this study was to provide more insight into the question as to why blockade of CCR1, CCR2, and CCR5 may have failed in clinical trials in rheumatoid arthritis (RA) patients, using an in vitro monocyte migration system model." (PMID 21747955, 2011). "Therefore, the results do not support the view that CCR2 antagonists are sufficient to induce clinical improvement in rheumatoid arthritis, and these studies were discontinued." (PMID 36566220, 2022). "In addition, the blockade of CCL2 receptor CCR2 via human CCR2 blocking antibodies displayed up to 94% reduction of free CCR2 on monocytes, but without an amelioration of synovial inflammation in rheumatoid arthritis." (PMID 33540898, 2021). "Besides, CCR2 surface expression on neutrophil is not specific to sepsis or infection and can be found in other conditions, such as rheumatoid arthritis, and ischemic liver injury." (PMID 33424860, 2020). "CCR2 is a chemokine receptor for monocyte chemoattractant protein-1 (MCP-1 or CCL2) and important for monocyte trafficking toward sites of inflammation, a process that is critical for autoimmune diseases like rheumatoid arthritis (RA) and CIA." (PMID 21991368, 2011).
hepatocellular carcinoma (45 papers, 2012 to 2026). A malignant tumor that arises from hepatocytes. "In hepatocellular carcinoma mouse models, the number and size of tumor foci are significantly attenuated in CCR2-deficient mice compared with those in wild-type mice." (PMID 39516356, 2024). "Furthermore, in a model of liver cancer, senescent cell surveillance was shown to require the recruitment and maturation of CCR2+ myeloid cells, while the ablation of CCR2 caused outgrowth of hepatocellular carcinomas." (PMID 33352064, 2020). "Investigate how SLFN11 affects the response to immunotherapy by regulating immune cell infiltration (such as T cells and macrophages) or cytokine secretion (such as the CCL2/CCR2 axis), especially in hepatocellular carcinoma and ovarian cancer." (PMID 40766331, 2025). "Senescent tumor cells recruit CCR2-positive myeloid cells, enhancing hepatocellular carcinoma growth and worsening the prognosis of patients with hepatocellular carcinoma through NK cell inhibition." (PMID 35053408, 2022). "Targeting and suppression of tumor‐infiltrating macrophages via CCL2/CCR2 signaling was a therapeutic strategy against hepatocellular carcinoma." (PMID 36039642, 2022). "In murine models of hepatocellular carcinoma, combined treatment with the CCR2 antagonists, RDC018 or 747, with sorafenib was validated to inhibit tumor growth and metastasis, accompanied by a significant reduction of macrophage infiltration." (PMID 33463063, 2021). "A preclinical study in hepatocellular carcinoma assessing the blockade of CCL2/CCR2 with the CCR2 antagonist RDC018 revealed hindered tumor growth and metastasis, reduced postsurgical recurrence, and prolonged survival." (PMID 34575965, 2021). "Senescence-recruited CCR2 positive myeloid cells enhance hepatocellular carcinoma growth and worsen the prognosis of patients with hepatocellular carcinoma through NK cell inhibition." (PMID 34458273, 2021). "Further illustrating the relevance of MCP-1 in relation to macrophages, it was shown that CCR2 antagonists inhibit HCC growth in an orthotopic mice model where murine hepatoma cells were implanted in the liver." (PMID 34638361, 2021). "In turn, a natural CCR2 antagonist, 747, alone exhibited anticancer properties and potentiated the antitumor efficacy of a low dose of sorafenib in a mouse model of hepatocellular carcinoma." (PMID 34575965, 2021). "A recent report showed a reduction of CCL2/CCR2 signaling inhibited macrophage infiltration and M2-polarization in hepatocellular carcinoma." (PMID 33156861, 2020). "Shi M et alfound a three-gene expression signature associated to early human hepatocellular carcinoma, constituted by the chemokine (C-X-C motif) receptor 2 (CXCR2), C–C chemokine receptor type 2 (CCR2) and the E1A-Binding Protein P400 (EP400)." (PMID 26317806, 2015). "In the liver, CCR2 is involved in multiple stages of liver pathology, including acute liver injury and chronic hepatitis, fibrosis/cirrhosis, and tumor progression, making it a potential therapeutic target for hepatocellular carcinoma (HCC)." (PMID 35281057, 2022). "In addition, CCL2 in hepatocellular carcinoma (HCC) models attracts CCR2+ myeloid cells that stimulate SC clearance via immunosurveillance but can promote the growth of already established HCC cells by inhibiting NK cell–mediated clearance of cancer cells." (PMID 35775492, 2022). "Generally speaking, the rationale of the present study is to design a novel anticancer therapy using bevacizumab (avastin; AV) and CCR2 inhibitor (CR)-encapsulated nanoparticles and applied them against hepatocellular carcinoma (HepG2 and Huh-7) and non-small cell lung cancer (A549) cell lines." (PMID 31350989, 2019). "Small molecule inhibitors targeting TAMs are emerging as a strategic approach in the treatment of hepatocellular carcinoma (HCC), focusing on key pathways such as CCR2 and p38 MAPK to deplete or modulate TAMs." (PMID 39796695, 2024).
hepatocellular carcinoma (continued). "CCL2 is prognostic for hepatocellular carcinoma (HCC), where targeting TAMs via CCL2/CCR2 blockade effectively reduces tumour growth, reverses the immunosuppressive TME, and enhances cytotoxic T-cell responses." (PMID 40683913, 2025). "In hepatocellular carcinoma, the CCL2/CCR2 axis promotes macrophage infiltration and forms an immunosuppressive microenvironment." (PMID 36018370, 2023). "In murine models of hepatocellular carcinoma (HCC), CCR2 targeting with the antagonists RDC018 or 747 in combination with Sorafenib, reduced tumor growth and metastasis with a corresponding decrease in macrophage infiltration." (PMID 30894861, 2019). "Small-molecule antagonists against CCR2/CCR5 have been investigated in certain types of cancer, and only BMS-813160 is in a phase 2 study (NCT04123379), which has been applied to non-small cell lung cancer and hepatocellular carcinoma." (PMID 39516356, 2024). "Furthermore, BMS-813160, a CCR2/CCR5 dual antagonist, has been studied in combination treatments in non-small cell lung cancer (NSCLC), hepatocellular carcinoma (HCC), and pancreatic ductal adenocarcinoma (NCT04123379, NCT03496662)." (PMID 35158779, 2022). "For the S100A8 partnering protein S100A9, it was suggested that it is expressed by CCR2+ TAMs in hepatocellular carcinoma (HCC), where CCR2+ TAMs presented the same expression pattern as S100A9+ TAMs and were co-localized with CD31+ endothelial cells in areas of dense vascularisation." (PMID 34209679, 2021). "A recent study found that application of the CCR2 antagonist inhibited the tumorigenicity via reducing the infiltration of TAMs and increasing the infiltration of cytotoxic CD8 positive lymphocytes in a murine hepatocellular carcinoma model." (PMID 31024838, 2019). "It is reported that employing CCR2 antagonist inhibits monocyte/TAM recruitment and M2 polarization in hepatocellular carcinoma (HCC)." (PMID 33968014, 2021). "Furthermore, CCL2 induces hepatocellular carcinoma invasion and EMT via CCR2 activation." (PMID 33463063, 2021).
Arthritis (39 papers, 2005 to 2026). Inflammation of a joint. "This subset demonstrated enhanced osteoclastogenic activity in arthritis, whereas its migratory potential was susceptible to CCR2 blockade in vitro." (PMID 34925336, 2021). "CCR2+Vγ6+ γδ17 T cells played a pathogenic role in IL-1Ra-deficient (Il1rn–/–) mice, an IL-17-dependent spontaneous arthritis murine model." (PMID 33072104, 2020). "The upregulation of chemokine receptors Ccr1, Ccr2, and Ccr5 are associated with macrophage and endothelial cell infiltration in arthritis." (PMID 29197380, 2017). "CCR2 deficiency promoted exacerbated chronic erosive neutrophil dominated CHIKV-induced arthritis in mice." (PMID 28435679, 2017). "Furthermore, CCR2 deficiency in DBA/1J caused severe arthritis in CIA with cutaneous M. avium infection." (PMID 36860872, 2023). "However, most early arthritis genes in clusters C and D showed an expression peak later, at the acute phase of inflammation, and encoded chemokine receptors (Ccr2 and Ccr5) and chemokine ligands (Cxcl1, Ccl2, Ccl7, and Ccl9)." (PMID 15743466, 2005). "Our study demonstrated that the development of arthritis depends on the differentiation of CD2+MHC-II+CCR2+ myeloid precursors into highly proinflammatory mononuclear phagocytes." (PMID 41482544, 2026). "Psoriasis induced proinflammatory CD2+MHC-II+CCR2+ myeloid precursors to migrate from the skin to joints, but their migration alone was insufficient to induce arthritis." (PMID 41482544, 2026). "Adoptive transfer resulted in increased arthritis severity at this early time point, highlighting the critical proinflammatory role of CD2+MHC-II+CCR2+ myeloid precursors in an arthritis-conductive environment." (PMID 41482544, 2026). "Collectively these findings suggest that arthritis is controlled not only by the migration of CD2+MHC-II+CCR2+ myeloid precursors from the skin to the joint but also by CD200+ fibroblasts in the joint." (PMID 41482544, 2026). "CCR2+ monocytes are drivers of neutrophil extravasation into injured tissues not only in direct lung injury, but also, for example, during arthritis, as shown with intravital imaging." (PMID 40048367, 2025). "In an adjuvant-induced arthritis model of RA, CCR2, and the expression of other chemokines were increased, accompanied by increased activation of JAK/STAT1/STAT3 pathways, as well as macrophage and endothelial cell infiltration." (PMID 37457301, 2023). "We believe that our study contributes to the understanding of increased osteoclast activity associated with arthritis, by identifying two distinct OCP subsets according to the level of CCR2 expression." (PMID 36591261, 2022). "The link between mechanical strain and the onset of arthritis appears to depend on the local recruitment of Ly6high inflammatory monocytes elicited by the mechanostress-induced MCP-1/CCR2 axis." (PMID 35055107, 2022). "In our study, we rely on previously defined OCP subsets categorized by the level of CCR2 expression as circulatory-like committed CCR2hi OCPs, which are substantially expanded in arthritis, and marrow-resident CCR2lo OCPs of immature phenotype and behavior." (PMID 36591261, 2022). "Based on the proven importance of the CCL2/CCR2 axis in mouse and human OCP migration, we propose the addition of CCL2/CCR2 blockade early at the course of arthritis as a promising approach to reduce osteoresorptive damage." (PMID 34925336, 2021). "Alongside reducing clinical symptoms of arthritis and synovitis, as already described for CCR2/CCL2 blockade, SMI alone or in combination with MTX showed a decrease in bone loss, and the reduction of myeloid lineage cell accumulation locally and in spleen." (PMID 34925336, 2021). "In SPL of control mice, virtually all OCPs were double positive, with the increase in CCR2+CX3CR1- cell frequency in arthritis (right)." (PMID 34925336, 2021).
Arthritis (continued). "In conclusion, our study characterized the functional properties of two distinct OCP subsets in CIA, based on their CCR2 expression levels, implying that the CCR2hi circulatory-like subset is specifically induced by arthritis." (PMID 34925336, 2021). "Among the therapeutic options, inhibition of the CCL2/CCR2 chemokine axis holds great promise for controlling chronic painful arthritis." (PMID 33757529, 2021). "CCL12, a mouse-specific chemokine, also binds specifically to CCR2, and little is known about the role of this chemokine in clinical RA and murine experimental arthritis." (PMID 30937315, 2019). "Here, we found that γδ17 cells are the main producers of IL-17 in joints of Il1rn−/− mice, and that recruitment of CCR2+ γδ T cells to the joints via induction of CCL2 by CD4+ T cells is important for the development of arthritis." (PMID 26108163, 2015). "The severity of arthritis was approximately three times worse during the follow-up time period in CCR2−/− mice with deteriorated histological changes of leukocyte infiltration, bone erosion, and joint destruction." (PMID 21991368, 2011). "To confirm a role of IL-17 in the pathogenesis of CCR2-mediated exacerbation of arthritis, we examined the effect of a murine anti-IL-17A antibody on the development of CIA in CCR2−/− mice." (PMID 21991368, 2011). "In addition, collagen-induced arthritis in CCR2-null mice exhibited a more severe RA pattern, and it was confirmed that CCR2 also plays a protective role in RA." (PMID 36138477, 2022). "In fact, in K/BxN STIA, although systemic clodronate-mediated depletion of macrophages resulted in a drastic amelioration of the arthritis, CCR2 deficiency did not alter arthritis development whereas CX3CR1 deficiency produced exacerbated inflammation." (PMID 36300108, 2022). "Circulatory-like OCPs, which exhibit a high expression of the chemokine receptor CCR2 (hereafter abbreviated as CCR2hi), are substantially expanded in arthritis and present a significant source of highly osteoclastogenic cells attracted by the inflammatory environment to the affected bone." (PMID 36591261, 2022). "MIP-1α/CCL3 and RANTES/CCL5 demonstrated high constitutive expression on macrophages in adjuvant-induced arthritis, which correlated with the expression of CCR2 (MCP-1/CCL2 receptor) by macrophages and was proved to play an important role in maintaining inflammatory changes in the joints." (PMID 36293292, 2022). "Therefore, addition of CCL2/CCR2 blockade early in the course of arthritis is a promising approach to reduce bone pathology." (PMID 34925336, 2021). "Genetic ablation of CCL2 or pharmacologic targeting of its receptor CCR2 abates mechanically-induced exacerbation of arthritis, indicating that stress-induced chemokine release by mesenchymal cells and chemo-attraction of monocytes determines preferential homing of arthritis to certain hot spots." (PMID 30397205, 2018). "Studies of autoimmunity also suggest a role for CCR2 in Treg migration; in collagen induced arthritis animal models, blockade of CCR2 could prevent initiation of arthritis, but once established, exacerbated it by interfering with the function of CCR2+ Tregs." (PMID 29487602, 2018). "Furthermore, one study showed no clinical improvement in RA by blocking CCR2, whereas another study on a mouse model of RA surprisingly showed exacerbation of arthritis when CCR2 was knocked out." (PMID 24647150, 2014). "Neutralizing IL-17A has an ameliorating effect on the severe arthritis observed in CCR2−/− mice." (PMID 21991368, 2011). "Indeed, significant differences were identified over time for CCR2−/− mice in both the clinical arthritis scores (LRT = 26.4, df = 4, p<0.0001) and the paw swelling (LRT-37.5, df = 4, p<0.0001) compared to WT controls." (PMID 21991368, 2011).